CD68 (CD68 molecule)
Diseases named in the same sentence as CD68 in open-access papers (continued):
Sharing a sentence is not in itself a finding about the gene and the disease.
encephalitis (9 papers, 2013 to 2023). An acute inflammatory process affecting the brain parenchyma. "On neurohistology, parenchymal microglial aggregates (confirmed on CD68-immunostains in Cases 6–8) indicated subtle encephalitis." (PMID 35685741, 2022). "Contrarily to microglia found in most viral encephalitis, these extremely reactive microglia lost CD68 expression among regions with high viral loads." (PMID 35387656, 2022). "The immunopathological findings of anti-NMDAR encephalitis are increased deposits of immunoglobulin G and reactive microglial staining with anti-CD68 antibody, mainly in the basal forebrain, hippocampus, basal ganglion, and cervical spinal cord." (PMID 28056870, 2017). "A few days later (days 12–16), when the mice develop clinical signs of encephalitis, the expression of chemokines in the eye peaks and there is a clear increase in CD45, as well as increased expression of MHC, CD80, CD86, and CD68." (PMID 29802245, 2018). "In contrast, in chronic lesions CD68 + CD163+ macs are most highly represented in SIV-infected animals and in HIV-infected human with encephalitis." (PMID 25852823, 2015). "In the absence of treatment, encephalitis occurs in ~20-30% of infected individuals, which is characterized pathologically by the presence of multinucleated giant cells, microglia nodules, microgliosis, astrocytosis, and abundant CD68+ macrophages staining for HIV antigens." (PMID 25852823, 2015).
fibrosis (9 papers, 2011 to 2025). the formation of excess fibrous connective tissue in an organ or tissue in a reparative or reactive process. "Clinically, the active fragment GSDMD-N localizes primarily to CD68+ macrophages, and its renal level positively correlates with fibrosis severity across diverse CKD etiologies, reinforcing its pathogenic relevance." (PMID 41387110, 2025). "Cell population source analysis and immunofluorescence labeling showed that the mouse fibrosis model contained highly expressing Ccr2 and Cd68 cell populations." (PMID 37724132, 2023). "We found that metformin reduced the number of CD68-positive cells and CD68-mRNA expression in fibrosis-challenged hearts, suggesting a link between fibrotic and inflammatory responses to I/R injury." (PMID 34502314, 2021). "Moreover, CD68 and HLA-DR were upregulated 1.50-fold and 1.32-fold higher in advanced fibrosis compared to early-stage fibrosis." (PMID 36359782, 2022). "The cryostat muscle section was simultaneously incubated with CD206, CD68 (inflammatory), CD31 (vessels) and collagen type I (fibrosis) on the MACSima platform." (PMID 41160729, 2025).
Histiocytosis (9 papers, 2017 to 2026). An excessive number of histiocytes (tissue macrophages). "The histopathological tests of histiocytosis often show the presence of Cluster of differentiation 68( +) cells (CD68 is a protein expressed by cells in monocyte lineage, macrophages, and osteoclasts) along with varying amounts of tissue infiltration." (PMID 38376733, 2025). "Lymph nodes displayed moderate to severe capillary stasis and edema, an increased presence of extrafollicular plasmablasts, mild to moderate plasmacytosis, a dominant population of CD8+ T‐cells, and CD11c/CD68+ histiocytosis with hemophagocytic activity." (PMID 33950285, 2021). "In benign cephalic histiocytosis, the histiocytic infiltrate features dermal factor XIIIa and CD68." (PMID 39188505, 2024). "Therefore, the first attempt to characterize the skin biopsy fragments was made, a diagnosis of Lanherhans Cells Histiocytosis was discussed, based on CD68+++, CD 45+, MPO+, CD1a-, S-100-, desmin -, MY14-." (PMID 29450403, 2017).
IgA nephropathy (9 papers, 2016 to 2026). "The importance of CD-68-positive macrophages as a useful surrogate marker for endocapillary hypercellularity was earlier studied from Oxford University, in IgA nephropathy (IgAN)." (PMID 38612574, 2024). "In IgA nephropathy (IgAN), the presence of glomerular CD68+ cells was found to be a good surrogate marker for endocapillary hypercellularity." (PMID 35497794, 2022). "Similarly, research studies predicting response to immunosuppression in IgA glomerulonephritis showed that patients with higher glomerular CD68+ infiltrate density were 13 times more likely to respond to immunosuppression." (PMID 40338344, 2025). "In macrophages of patients with IgA nephropathy and macroscopic hematuria-related AKI, CD163 was associated with incomplete recovery of kidney function describing as the predominant subpopulations in kidney tissues, the M2a (CD206+/CD68+) and M2b (CD86+/CD68+) macrophages." (PMID 34307414, 2021). "In the study focusing on patients with IgA nephropathy, Xie and colleagues found that CD206+ and CD68+ macrophages infiltrated in the glomeruli were correlated to treatment response of immunosuppressive therapy." (PMID 36376784, 2022).
infarction (9 papers, 2017 to 2025). A localised pathological necrosis of tissue resulting from obstruction of the blood supply usually by a thrombus, an embolus, or vascular torsion. "A high number of CD68+ cells in the red pulp and reduced concentration of stabilin-1+ cells in the white pulp were associated with unfavorable post-infarction outcomes." (PMID 35629341, 2022). "Our data have revealed that brain-derived CCR5 deficiency leads to increased infarction size, increased neural degeneration, and decreased long-term inflammatory cell accumulation (Iba1+ cells and CD68+ cells) in the peri-infarct cortex 2 months after cortical ischemia." (PMID 33532129, 2021). "Immunofluorescence staining of CD68, a marker of macrophage, showed that there existed a large amount of CD68+-macrophage infiltration in the peri-infarction region in the MI group, while this phenomenon was attenuated in zr17-2 treated group." (PMID 38539067, 2024). "Immunofluorescence staining of CD68, a marker of macrophages, showed a large amount of CD68+ macrophage infiltration in the peri-infarction region in the MI group, while this phenomenon was attenuated in the sotagliflozin-treated group." (PMID 38058609, 2023). "We measured CD68‐positive staining to quantify the degree of the inflammatory macrophage infiltration during infarction pathogenesis." (PMID 28470940, 2017). "Expression of TREM2 and CD68 in cerebral infarcts of different ages." (PMID 28987033, 2018).
oral cancer (9 papers, 2014 to 2024). "The infiltration of tumor-associated CD68-positive macrophages and, in particular, tumor-promoting, M2-polarized, CD163-expressing macrophages was shown to be associated with oral cancer initiation and tumor progression." (PMID 35406584, 2022). "In accordance with other cancers, we observed cathepsin S production by both keratin+ tumor cells and CD68+ macrophages of oral cancer specimens collected from four patients." (PMID 34572924, 2021). "This study provides insights into the selection for early-stage oral cancer patients with concomitant high S100A9 with high CD68 in the stroma that most likely benefit from aggressive treatments." (PMID 26315114, 2015). "High expression of both S100A9 and CD68 proteins in tumor stroma was a strong poor prognostic marker for early-stage oral cancer patients." (PMID 26315114, 2015). "Taken together, the concomitant increase of both S100A9 and CD68 expression in tumor stroma served as poor prognostic markers for early-stage oral cancer patients." (PMID 26315114, 2015). "Tumor associated macrophages (TAMs) have been shown to promote tumorigenesis and metastasis, we used IHC staining to analyze the deregulation impact of CD68 together with S100A9 in tumor stroma on the clinical outcomes of 79 early-stage oral cancer patients." (PMID 26315114, 2015). "On the other hand, coherently with what we found, CD68+ cells seem to be associated with poor clinical outcomes, though no definite position on the role of CD68+ cells in oral cancer immune surveillance seems to be achieved." (PMID 34439365, 2021). "The expression of the myeloid cell marker CD115, as well as that of the macrophage markers CD68 and CD163, was significantly increased in oral cancer samples compared to healthy oral mucosa." (PMID 35406584, 2022). "Early-stage oral cancer patients with both high S100A9 expression and high CD68+ immune infiltrates in stroma had shortest recurrence-free survival, suggesting the use of both S100A9 and CD68 as poor prognostic markers for oral cancer." (PMID 26315114, 2015). "Early-stage oral cancer patients with both high S100A9 and high CD68 had the poorest clinical outcome relative to those with high expression of either protein alone, or those with low expression of both proteins." (PMID 26315114, 2015). "Following these findings, our results indicate that CD68 and CD163 may play important roles in carcinogenesis and progression in the patients of oral cancer." (PMID 24883329, 2014).
pancreatic ductal adenocarcinoma (9 papers, 2016 to 2025). An infiltrating adenocarcinoma that arises from the epithelial cells of the pancreas. "Tumor clinicopathological characteristic of patients with pancreatic ductal adenocarcinoma samples based on VISTA, CD68, and CD8 expression." (PMID 38357542, 2024). "Supporting the transcriptional data, we detected ZEB1 positive (+) CD68+ macrophages by immunofluorescence (IF) stainings of human CRC and mouse lung metastases formed upon tail vein injection (tvi) of pancreatic ductal adenocarcinoma (PDAC) cells." (PMID 40595293, 2025).
parasitemia (9 papers, 2016 to 2026). "Higher dose infection, with 2,000 or 20,000 sporozoites, showed equivalent parasitemia in CD68 KO and wild-type mice after day 9, arguing against parasitemia being a factor in the difference of CM development." (PMID 35073748, 2022). "In addition, blockage of galectin-receptor interactions leads to decreased host survival rate, increased peripheral blood parasitemia, increased parasite burden in the liver, and increased CD68+ macrophages and exacerbated liver pathology of Plasmodium berghei-infected mice." (PMID 35911679, 2022). "Our data indicate that blockage of galectin-receptor interactions may increase the activity of liver CD68+ macrophages in the erythrocytic stage of malaria, which is in agreement with the increased parasitemia and tissue parasite burden in malarial mice with α-lactose treatment." (PMID 34899708, 2021). "Immunohistochemistry for eight antibodies (CK19, CD3, Foxp3, CD20, Iba1, CD68, CD163, and CD204) was conducted to analyze the pathology of these parasitic infections." (PMID 32714946, 2020). "Blood parasitemia of WT and CD68 KO mice is not significantly different in low-dose infections such as mosquito biting or injection of 100 sporozoites." (PMID 35073748, 2022).
Rosai-Dorfman disease (9 papers, 2021 to 2026). "It is observed that both S100 and CD68 are diffusely positive in Rosai-Dorfman disease, Erdheim disease and Gaucher disease." (PMID 38502367, 2024). "The diagnostic criteria for Rosai-Dorfman disease are large histiocytic cells that stain positive for CD68 and S100, but negative for CD1a." (PMID 42016174, 2026). "Rosai-Dorfman disease was originally described as sinus histiocytosis with massive lymphadenopathy.This rare benign disorder is characterized by the proliferation of non-Langerhans histiocytes that exhibit emperipolesis, S100+, CD68+, CD30+, CD1a- and Langerin-." (PMID 38575975, 2024). "The histiocytosis, when present, most closely resembles Rosai-Dorfman disease (RDD), which is characterized by infiltrating CD68+, S100+, and CD1a− histiocytes." (PMID 33284430, 2021). "Rosai-Dorfman disease histiocytes are typically positive for CD68, CD163, and S100, while negative for CD1a and langerin." (PMID 40398847, 2025). "Rosai-Dorfman Disease (RDD), also known as sinus histiocytosis with massive lymphadenopathy, is an uncommon histiocytic condition characterized by massive histopathological aggregation of CD1-a negative, CD68-positive, and S100-positive histiocytes." (PMID 36960255, 2023).
schizophrenia (9 papers, 2019 to 2022). A major psychotic disorder characterized by abnormalities in the perception or expression of reality. "In summary, in the schizophrenia group, associations of CD68 vs. Iba1, of CD68 vs. CD32b, of Iba1 vs." (PMID 34339805, 2021). "Central neuro-inflammation, with its characteristic swollen microglia expressing CD68, is not only causal to the age-related loss of neurons, but also implicated in psychiatric diseases such as schizophrenia." (PMID 31422380, 2019). "Previous literature looking at CD68 expression in control and schizophrenia cases has reported ambiguous outcomes." (PMID 36139363, 2022). "IBA1 and CD68 mRNAs were reduced in bipolar disorder compared to both controls (17–26%, all p ≤ 0.046) and schizophrenia (21–32%, all p ≤ 0.030)." (PMID 34911938, 2021). "Of note, a metaanalysis on multiple schizophrenia studies most of which conducted with the CD68- and HLA-DR-antibody indicated an increase in microglial densities in many brain areas, but also showed remarkable heterogeneity between the studies." (PMID 32062729, 2020). "However, increased AIF1, CD68, and TSPO mRNA was identified in high immune schizophrenia cases, although the number of microglia per se seemed unchanged." (PMID 31168068, 2021).
serous ovarian cancer (9 papers, 2014 to 2023). "As for serous carcinoma, total CD68+ macrophage infiltration together with CD163 expression was significantly increased in high-grade serous ovarian cancer (HGSOC) compared to low-grade serous ovarian cancer (LGSOC)." (PMID 33194645, 2020). "The obtained immunostaining results indicated that CD68+ TAM density was highest in serous ovarian cancer followed by mucinous, undifferentiated, endometrioid, and clear cell cancers (p = 0.049, ANOVA)." (PMID 24507759, 2014). "Here, we used immunohistochemical (IHC) staining and 7-color multiplex staining to evaluate CD8 (cluster of differentiation 8), CD68, PD-L1 (programmed death-ligand 1), CD34, FAP (fibroblast activation protein), and cytokeratin in 220 tissue cores from 26 high-grade serous ovarian cancer samples." (PMID 31772388, 2019).
ulcerative colitis (9 papers, 2010 to 2025). An inflammatory bowel disease involving the mucosal surface of the large intestine and rectum. "We next examined NR4A1 and NLRP3 activation in intestinal tissue sections from patients with ulcerative colitis and found increased activation of these proteins in CD68+ macrophages in active UC compared to remission." (PMID 40596758, 2025). "Other authors have reported increased number of CD68+ macrophages in tissue sections either from biopsies specimens of Crohn’s disease or ulcerative colitis patients or from intestines of DSS-treated mice, corroborating our data." (PMID 33519451, 2020). "The results of the present study were similar to those of a previous study wherein ECM hydrogel delivered via enema for 1 week down-regulated TNFα+/CD68+ macrophages in a rat model of ulcerative colitis, another chronic inflammatory-driven disease of the GI tract." (PMID 32656339, 2020). "Allicin can regulate CD68, MPO, MDA, and inflammation factor expression to attenuate DSS-induced ulcerative colitis, and its mechanism may be related to the regulation of signal transducer and activator of transcription 3 (STAT3) and nuclear factor-κB (NF-κB) signaling pathway activity." (PMID 31139644, 2019).
Anxiety (8 papers, 2019 to 2025). Intense feelings of nervousness, tension, or panic often arise in response to interpersonal stresses. "Together, such drug studies support an association between reduced brain CD68 expression and attenuated anxiety." (PMID 32732969, 2020). "In support of a link between hippocampal CD68 and hyperanxiety, Abuelezz and colleagues found that adverse environmental stress (chronic unpredictable mild stress, CUMS) increases CD68+ cell counts in the hippocampus in association with increased anxiety behavior." (PMID 36361832, 2022). "Taken together, the CD68+ marker of microglial phagocytic activation is present in brain tissue during the late phase of AD, when anhedonia and anxiety are observed." (PMID 40801621, 2025). "In particular, the dentate gyrus (DG) of the hippocampus of HABs exhibited enhanced density and average cell area of Iba1+, and density of phagocytic (CD68+/Iba1+) microglia compared to normal anxiety (NAB) controls." (PMID 32732969, 2020). "Consequently, upon systemic administration of the anti-oxidant and anti-inflammatory, coenzyme-Q10 displayed a reduction in CUMS-induced anxiety and in hippocampal CD68+ cell count." (PMID 36361832, 2022). "Furthermore, evidence also suggested that anxiety-like behavior is accompanied by microglial activation, that is, an enhanced number of Iba1+ and CD68+ cells." (PMID 31863052, 2019). "Furthermore, among the highly myopic patients, those with anxiety (total anxiety score ≥ 7) also had higher ratios of monocytes (7.77 ± 2.15% vs 4.16 ± 1.10%, respectively, P = 0.0032) and CD14+/CD68+ monocytes (7.71 ± 2.12% vs 3.74% ± 1.65%, respectively, P = 0.0064) than those with no anxiety." (PMID 37699875, 2023).
astrocytoma (8 papers, 2011 to 2023). "This is in line with a study by Klein el al.41, who reported on a immunohistochemical double-labeling study with Ki-67 as proliferation-marker and Ki-M1P (CD68) as microglia marker in 40 astrocytomas WHO grade I-IV." (PMID 34504133, 2021). "We found that the anti-inflammatory effects of CR in the CT-2A astrocytoma were associated with (i) reduced nuclear NF-κB activation and subsequent DNA binding to promoters of proinflammatory genes, (ii) reduced COX-2 and AIF-1 expression, (iii) reduced CD68 and MIP-2 expression." (PMID 21479220, 2011). "They found that CD163 and CD68, as well as S100A9 rates were elevated in dexamethasone-treated grade I astrocytoma and GBM compared to normal brain tissue and grades II and III tumors." (PMID 33204365, 2020). "On the other hand, CD68+, but not F4/80+, TAMs prefer to accumulate in PIMO+ hypoxia in intracranial ALTS1C1 astrocytoma." (PMID 22888475, 2012).
endometrial cancer (8 papers, 2012 to 2024). Primary or metastatic malignant neoplasm involving the endometrium (mucous membrane that lines the endometrial cavity). "The study also found that the density of CD68-positive macrophages in endometrial cancer tissue is higher than that in normal endometrial tissue." (PMID 37780629, 2023). "The levels of infiltrating tumor-associated macrophages (CD68+ and CD163+ cells) positively correlate well with aggressive endometrial cancer as infiltration of such cells progressively increases from normal endometrium to hyperplastic to endometrial cancer." (PMID 31426393, 2019). "We performed immunohistochemistry of the TME proteins, PD-L1, PD-1, CD4, CD8, CD68, and VEGF in endometrial carcinomas from 221 patients." (PMID 32066405, 2020). "In endometrial cancer, CK (AE1/AE3) and vimentin are positive, while CD68 is negative, and the Ki67 proliferation index is significantly greater than that in malacoplakia." (PMID 38895183, 2024).